GABARAPL1 (GABA type A receptor associated protein like 1)
Description:
Ubiquitin-like modifier that increases cell-surface expression of kappa-type opioid receptor through facilitating anterograde intracellular trafficking of the receptor. Involved in formation of autophagosomal vacuoles. While LC3s are involved in elongation of the phagophore membrane, the GABARAP/GATE-16 subfamily is essential for a later stage in autophagosome maturation. Through its interaction with the reticulophagy receptor TEX264, participates in the remodeling of subdomains of the endoplasmic reticulum into autophagosomes upon nutrient stress, which then fuse with lysosomes for endoplasmic reticulum turnover.
Synonyms: GEC1; APG8L; ATG8L; ATG8B; APG8-LIKE; ATG8
Tractability: Small molecule: a structure with a bound ligand is known; it has a binding pocket of medium quality. Antibody: its Gene Ontology location is reachable by antibodies, with high confidence. PROTAC: ubiquitination databases record sites on it; its protein half-life has been measured.
Gene: Protein-coding gene on chromosome 12 (10,212,458 to 10,223,128, forward strand). Ensembl gene ENSG00000139112.
Subcellular location: Cytoplasmic vesicle, autophagosome; Cytoplasmic vesicle membrane; Cytoplasm, cytoskeleton; Endoplasmic reticulum; Golgi apparatus
Subcellular location (Human Protein Atlas): Vesicles; Basal body; Cytosol; Plasma membrane; Primary cilium
Pathways (Reactome):
Autophagy: Macroautophagy
Gene Ontology:
Molecular function: phospholipid binding; protein binding; Tat protein binding; ubiquitin protein ligase binding; beta-tubulin binding; GABA receptor binding; phosphatidylethanolamine binding
Biological process: autophagosome assembly; autophagosome maturation; cellular response to nitrogen starvation; mitophagy; glycophagy
Cellular component: autophagosome; cytoplasmic vesicle membrane; mitochondrion; autophagosome membrane; cytosol; endoplasmic reticulum; Golgi apparatus; cytoskeleton
Genetic constraint (gnomAD): Loss-of-function variants: 2 observed, 8.53 expected, observed/expected ratio (o/e) 0.23, 90% interval 0.095 to 0.74. That is too few expected variants to judge how well the gene tolerates losing a copy. Missense variants: 57 observed, 91.52 expected, observed/expected ratio (o/e) 0.62, 90% interval 0.5 to 0.78. Synonymous variants: 38 observed, 33.57 expected, observed/expected ratio (o/e) 1.13, 90% interval 0.87 to 1.48.
Homologues: Orthologues: chimpanzee GABARAPL1 (100% identical), guinea pig GABARAPL1 (100% identical), mouse Gabarapl1 (100% identical), tropical clawed frog gabarapl1 (100% identical), pig GABARAPL1 (99% identical), macaque GABARAPL1 (83% identical), dog GABARAPL1 (82% identical), rat Gabarapl1 (82% identical), zebrafish map1lc3cl (38% identical), Caenorhabditis elegans lgg-2 (32% identical). Paralogues in human: GABARAP (86% identical), GABARAPL2 (61% identical), MAP1LC3C (38% identical), MAP1LC3A (34% identical), MAP1LC3B (32% identical), MAP1LC3B2 (32% identical).
Diseases named in the same sentence as GABARAPL1 in open-access papers:
GABARAPL1 is named in the same sentence as 78 diseases in open-access papers, as found by Europe PMC text mining. Sharing a sentence is not in itself a finding about the gene and the disease. The quoted sentences say what the papers report.
breast carcinoma (25 papers, 2010 to 2025). "In breast cancer, neuroblastoma, hepatocellular carcinoma, and lung adenocarcinoma, higher expression levels of GABARAPL1 correlate with reduced risk of tumor metastasis and improved patient survival rates." (PMID 41040512, 2025). "A comprehensive analysis of breast cancer biopsies in a cohort study revealed a significant association between lower GABARAPL1 expression and an increased risk of recurrence." (PMID 37521346, 2023). "A study of a cohort of breast cancer biopsies demonstrated that lower GABARAPL1 expression in breast cancer was associated with a higher risk of recurrence." (PMID 34252149, 2021). "GABARAPL1, as a tumor suppressor protein in breast cancer, is associated with a better outcome for patients with lymph node-positive breast cancer." (PMID 33194339, 2020). "In breast cancer the expression of GABARAPL1 was associated with DNA methylation and histone deacetylation." (PMID 29088804, 2017). "Our laboratory previously demonstrated that GABARAPL1 associates with autophagic vesicles, regulates autophagic flux and acts as a tumor suppressor protein in breast cancer." (PMID 28915569, 2017). "Our data demonstrated that a specific decrease of GABARAPL1 expression in breast cancers was associated with both DNA methylation and histone deacetylation and that CREB-1 recruitment on GABARAPL1 promoter was required for GABARAPL1 expression." (PMID 26474850, 2015). "Similarly, combined 5-aza-dC and TSA (trichostatin A) treatments restored GL1 (GABARAPL1, GABA type A receptor-associated protein like 1) expression in breast cancer cell models." (PMID 31861179, 2019). "The inhibition of GABARAPL1 in breast cancer cells has been reported to result in a reduction in autophagy flux and impaired clearance of damaged mitochondria." (PMID 40095893, 2025). "Overexpression of GABARAPL1 exerted inhibitory effects on cell proliferation, colony formation, and invasion in breast cancer cells in-vitro." (PMID 37521346, 2023). "Previous study indicated that GABARAPL1 acts as a tumor suppressor protein, and showed that it inhibited cell proliferation, invasion and tumor growth in breast cancer and prostate cancer." (PMID 36062307, 2022). "GABARAPL1 is suggested to be a tumor suppressor and its lower levels have been reported to be related to a poor prognosis in liver and breast cancer patients." (PMID 36292980, 2022). "Nevertheless, our team has previously shown that, in breast cancer cell lines, GABARAPL1 is involved in autophagic flux." (PMID 34681055, 2021). "Recent studies have reported that GABAA receptor-associated protein-like 1 (GABARAPL1) promotes the growth and metastasis of breast cancer cells via metadherin (MTDH)." (PMID 34445736, 2021). "Overexpression of GABARAPL1 can inhibit cell proliferation, colony formation, and invasion in breast cancer cells in-vitro." (PMID 34252149, 2021). "GABARAPL1 overexpression inhibits cell proliferation, colony formation and invasion in breast cancers in vitro." (PMID 32801338, 2020). "Next, we set out to determine the functional implications of the induced GABARAPL1 expression in basal-like breast cancer cells." (PMID 32801338, 2020). "We revealed a previously unappreciated role of GABARAPL1 as a regulator in the specification of breast cancer subtypes that is dependent on ERβ levels." (PMID 32801338, 2020). "In this study, our findings reveal a previously unappreciated role for GABARAPL1 as a determinant of the molecular subtype of breast cancer." (PMID 32801338, 2020). "It has been reported that Dip G targets the CHIP E3 ubiquitin ligase and reciprocally controls ERα and ERβ protein stability in breast cancer cells, and that GABARAPL1 is identified as an early estrogen-induced gene." (PMID 32801338, 2020). "Similar results were reported in breast cancer and hepatocellular carcinoma, highlighting a role of GABARAPL1 as a tumor suppressor." (PMID 31803623, 2019).
breast carcinoma (continued). "To do so, we used the breast cancer cell line MCF-7 overexpressing GABARAPL1 or GABARAPL1 G116A mutant protein in which the essential C-terminal glycine at position 116 has been replaced by an alanine." (PMID 28915569, 2017). "We have previously shown in our laboratory that cancer cell lines present a reduced GABARAPL1 expression compared to normal cells and that a high GABARAPL1 expression is correlated with a good prognosis in breast cancer patients." (PMID 28915569, 2017). "We found that GABARAPL1 was highly expressed in breast cancer cell lines, particularly in TNBC cell lines." (PMID 29088804, 2017). "In a previous study, we demonstrated that a cellular knock-down of GABARAPL1 decreased autophagic flux and lysosome number in the breast cancer cell line MDA-MB-436." (PMID 28915569, 2017). "We next wanted to confirm the effects of GABARAPL1 and GABARAPL1 G116A on cell cancer phenotype in a second breast cancer cell lines." (PMID 28915569, 2017). "In addition, our findings identified GABARAPL1 as an ERβ-dependent regulator of the molecular subtype of breast cancer." (PMID 32801338, 2020). "Dip G has a robust GABARAPL1-inducing activity in basal-like breast cancer cells." (PMID 32801338, 2020). "It has been shown that GABARAPL1 is a tumor suppressor and this function to be independent of autophagosome formation in hormone responsive breast cancer cells.Moreover, the latest study shows that GABARAPs and LC3s play contrasting roles while regulating ULK1 for autophagy initiation." (PMID 34621117, 2020). "In addition, our data identified GABARAPL1, whose expression was increased by Dip G in an ERβ-dependent manner, as a functional regulator of the molecular subtype of breast cancer." (PMID 32801338, 2020). "We and other researchers previously observed reduced GABARAPL1 expression in CaP, breast cancer and hepatocellular carcinoma, suggesting that GABARAPL1 may serve as a tumor suppressor." (PMID 31803623, 2019). "It has been shown that estrogens may influence the expression of GABARAPL1 and hence may be involved in a variety of estrogen-sensitive diseases such as breast cancer." (PMID 30374741, 2018). "Moreover, we have demonstrated that GABARAPL1 overexpression inhibits cell proliferation, colony formation and invasion of breast cancer cells in vitro." (PMID 28915569, 2017). "And GABARAPL1 is required for maintaining normal autophagic flux in breast cancer." (PMID 29088804, 2017). "Since GABARAPL1 has also been described as a tumor suppressor protein in breast cancer, we then wondered whether the tumor suppressive function of GABARAPL1 require its conjugation to autophagosomes." (PMID 28915569, 2017). "Furthermore, the G116A mutation did not alter the effect of GABARAPL1 on cell proliferation and migration phenotypes in another breast cancer cell line BT474 in vitro." (PMID 28915569, 2017). "In this study, we aimed to determine whether GABARAPL1 conjugation to autophagosomes is necessary for its tumor suppressive functions using the MCF-7 breast cancer cell line overexpressing GABARAPL1 or a G116A mutant, which is unable to be lipidated and associated to autophagosomes." (PMID 28915569, 2017). "GABARAPL1 and autophagy GSEA pathway gene signatures were affected under increasing compression in breast cancer cells." (PMID 39746759, 2025). "Additionally, mTOR-independent non-canonical autophagy was reported to provide stress resistance to neuroblastoma and breast cancer cells, suggesting selenite may induce protective autophagy in HCT116 cells via AMPK/GABARAPL-1 related pathways without affecting mTOR." (PMID 35201430, 2021).
hepatocellular carcinoma (12 papers, 2017 to 2025). A malignant tumor that arises from hepatocytes. "However, in certain cancers, high levels of GABARAPL1 expression are associated with better results, such as hepatocellular carcinoma (HCC) and node-positive breast cancer." (PMID 34759953, 2021). "And overexpression of GABARAPL1 has been shown to inhibit tumor cell proliferation in hepatocellular carcinoma (HCC) cell lines and may be associated with prognosis." (PMID 40900801, 2025). "As an autophagy-related gene, GABARAPL1 is frequently down-regulated in a variety of tumor types, such as hepatocellular carcinoma and breast cancer." (PMID 38234672, 2024). "But in some cancers, high expression level of GABARAPL1 was related with better outcomes, such as hepatocellular carcinoma and lymph node-positive breast cancer." (PMID 29088804, 2017). "But in hepatocellular carcinoma and lymph node-positive breast cancer high expression level of GABARAPL1 is related with better outcomes." (PMID 29088804, 2017). "It had been reported that lower GABARAPL1 expression is correlated with poor prognosis of hepatocellular carcinoma and lymph node-positive breast cancer patients, which might indicate that GABARAPL1 is a negative regulator of cancer progression." (PMID 33682883, 2021). "Though the prognosis significance of the autophagy gene GABARAPL1 in NPC patients has not been studied yet, low expression of GABARAPL1 has been demonstrated to be associated with poor prognosis in hepatocellular carcinoma and lymph node-positive breast cancer." (PMID 38234672, 2024). "Additionally, high GABARAPL1 expression has been linked to poor prognosis in TNBC and HNSC, yet paradoxically, elevated expression correlates with longer overall survival in certain cancers, including hepatocellular carcinoma and lymph node-positive breast cancer." (PMID 40951345, 2025).
prostate carcinoma (9 papers, 2017 to 2025). A carcinoma that arises from epithelial cells of the prostate gland. "In prostate cancer, GABARAPL1 is regulated by the androgen receptor (AR), which affects the proliferation of prostate cancer cells." (PMID 40900801, 2025). "Transcriptional regulation of GABARAPL1 (GABA type A receptor associated protein like 1), as an autophagy modulator, can be mediated via androgen, and the proliferation of prostate cancer cells is delayed by inhibiting autophagy." (PMID 35317831, 2022). "Androgen deprivation leads to GABARAPL1 downregulation, subsequent induction of autophagy (GABARAPL1 is autophagy repressive in this context) and increased survival and proliferation of prostate cancer cells." (PMID 35317831, 2022). "Future studies are needed to elucidate exactly how GABARAPL1 inhibits prostate cancer cell invasion through autophagy pathway." (PMID 27966458, 2017). "Knockdown of GABARAPL1, an early estrogen-regulated gene belonging to the GABARAP family, inhibits AR-positive prostate cancer growth." (PMID 36937439, 2023). "A potential role of decreased autophagy in promoting prostate cancer progression has been suggested through correlations between low prostate tumour expression of the core ATG genes FIP200, ATG16L1, or GABARAPL1 and poor prognosis in clinical prostate cancer cohorts." (PMID 38910881, 2024).
gastric cancer (5 papers, 2020 to 2022). A primary or metastatic malignant neoplasm involving the stomach. "For example, miR133a-3p blocks the glutamine metabolism in gastric cancer, targeting gamma-aminobutyric acid receptor-associated protein-like 1 (GABARAPL1) and inhibiting autophagy, a process by which gastric cancer cells recycle glutamine." (PMID 33808190, 2021). "MicroRNA-133a-3p targets GABARAPL1 (gamma-aminobutyric acid receptor-associated protein-like 1) to inhibit autophagy-mediated glutaminolysis, thereby inhibiting metastasis of gastric cancer." (PMID 32547948, 2020). "For example, miR-133a could target GABA type A receptor associated protein like 1 (GABARAPL1) to inhibit autophagy-mediated glutaminolysis, repressing gastric cancer growth and metastasis." (PMID 35012539, 2022). "Quercetin-induced autophagy decreased its therapeutic effect in gastric cancer cells. miR-143 targeting GABARAPL1 effectively inhibited autophagy in gastric cancer cell lines, which could improve the efficacy of quercetin." (PMID 36467088, 2022). "Another study demonstrated that quercetin-induced autophagy reduced its therapeutic effect on gastric cancer (GC) cells, and treatment with quercetin combined with miR-143 agonist, an inhibitor of autophagy in GC cells targeting GABARAPL1, could improve the antitumor efficacy of quercetin." (PMID 36467088, 2022).
lung adenocarcinoma (5 papers, 2015 to 2025). A carcinoma that arises from the lung and is characterized by the presence of malignant glandular epithelial cells. "Next, we investigated the protein levels of GABARAP and GABARAPL1 by IHC in 60 samples of lung adenocarcinomas." (PMID 34681055, 2021). "IHC experiments, which were conducted in a cohort of patients presenting lung adenocarcinomas, showed high GABARAPL1 and low UPF1 levels in EMT+ tumors." (PMID 34680418, 2021). "In our study, we found that ATG8 expression is correlated with EMT markers, and that GABARAPL1 is the gene most correlated with the EMT markers in lung adenocarcinoma tumors." (PMID 34681055, 2021). "Similarly, the lower expression of GABARAPL1 and RFK was associated with improved OS in lung adenocarcinoma patients." (PMID 35574381, 2022). "Moreover, amongst the ATG8 family, GABARAPL1 expression presented the greatest increase in expression during TGF-β/TNF-α-induced EMT in A549 lung adenocarcinoma cells." (PMID 34681055, 2021). "Similarly, the induction of EMT in the A549 lung adenocarcinoma cell line using TGF-β/TNF-α led to a high increase in GABARAPL1 expression mediated by the EMT-related transcription factors of the SMAD family, whereas the other ATG8 genes were less modified." (PMID 34681055, 2021). "Altogether, these interesting results support our hypothesis that GABARAPL1 expression is correlated with classical EMT markers at both the mRNA and protein levels in human lung adenocarcinoma." (PMID 34681055, 2021). "Our observations have also been confirmed in A549 lung adenocarcinoma cells and in MCF10A immortalized breast cells with induced EMT, where ATG8 gene expression was modulated during EMT, but amongst them, GABARAPL1 appeared to be the most highly expressed gene." (PMID 34681055, 2021). "We therefore analyzed a cohort of lung adenocarcinoma tumors using transcriptome analysis and immunohistochemistry, and found that the expression of ATG8 genes is correlated with that of EMT-related genes, and that GABARAPL1 protein levels are increased in EMT+ tumors compared to EMT- ones." (PMID 34681055, 2021).
myocardial infarction (5 papers, 2020 to 2025). Gross necrosis of the myocardium, as a result of interruption of the blood supply to the area, as in coronary thrombosis. "The findings revealed a significant upregulation in the protein and mRAN expression levels of ACSL1, IL1B, and GABARAPL1 in both the hypoxic cell model and myocardial infarction animal model compared to the control group." (PMID 40287718, 2025). "GABARAPL1 has also been reported to be involved in autophagy signaling in myocardial infarction-induced muscle atrophy in rats." (PMID 32597946, 2020).
neuroblastoma (5 papers, 2009 to 2025). Neuroblastoma (NB) is the most common solid, extracranial childhood tumor. "To determine whether LC3 and Gabarapl1 are also transcriptionally regulated by FOXO3 in neuroblastoma cells we measured the mRNA expression of LC3 and Gabarapl1 in SH-EP/FOXO3-shCtr and SH-EP/FOXO3-shDEPP-13 cells by quantitative RT-PCR analyses." (PMID 28545464, 2017).
diabetes (4 papers, 2013 to 2025). "Our study aligns with previous research that has reported alterations in GABARAPL1 expression in in vitro models relevant to AD, as well as in cellular models of AD and type 2 diabetes mellitus comorbidity." (PMID 40002775, 2025). "Our results were consistent with a previous study that reported the upregulation of mRNA expression of LC3, Gabarapl1, and Cathepsin L in the skeletal muscle of diabetic rats and uremia rats induced by subtotal nephrectomy." (PMID 24303049, 2013). "FOXO family proteins play a vital role in the development of muscle atrophy by activating the ubiquitin-mediated proteolysis pathways including the regulation of FBXO32/Atrogin-1 and TRIM63/MuRF1, and dependently regulate BNIP3L and GABARAPL1 in a STZ-diabetes model." (PMID 32806520, 2020).
breast adenocarcinoma (3 papers, 2010 to 2017). "GABARAPL1 expression level is associated with higher histological grade and lower risk of metastasis in breast adenocarcinoma patients, specifically for lymph node-positive patients." (PMID 27966458, 2017). "Nevertheless, the analysis of GABARAPL1 expression in a cohort of 256 breast adenocarcinoma revealed that a low GABARAPL1 expression was correlated with a high risk of metastasis, in particular for lymph node-positive patients." (PMID 26474850, 2015).